GCH1 (GTP cyclohydrolase 1)
Diseases named in the same sentence as GCH1 in open-access papers (continued):
Sharing a sentence is not in itself a finding about the gene and the disease.
cervical cancer (2 papers, 2023 to 2026). A primary or metastatic malignant neoplasm involving the cervix. "Collectively, these results demonstrate that GCH1 is associated with more aggressive phenotypes in cervical cancer, suggesting its oncogenic role in cervical cancer." (PMID 41583517, 2026). "In the TME of cervical cancer, GCH1 was positively linked with M1 macrophages and CD8+ T cells." (PMID 41583517, 2026). "In this study, we performed a thorough investigation of ferroptosis-related genes and identified the functional complexity of GCH1 during tumorigenesis in cervical cancer." (PMID 41583517, 2026). "Through bioinformatics analysis, we discovered that GCH1 and H1.2 are key ferroptosis-related molecules in cervical cancer." (PMID 41583517, 2026). "GCH1 knockdown impaired growth, migration and invasion and promoted apoptosis in cervical cancer cells, possibly through the inhibition of the phosphorylated PI3K/AKT/mTOR signaling pathway." (PMID 41583517, 2026). "GCH1 expression was detected in cervical cancer cell lines using WB, and GCH1 was more highly expressed in SiHa and CaSki cells." (PMID 41583517, 2026). "The differential expression of the key genes GCH1 and H1-2 between cervical cancer tissues and normal cervical tissues was further substantiated using the GSE7410 and GSE7803 datasets." (PMID 41583517, 2026). "IHC of the tissue microarray (TMA) and immunofluorescence spatial distance evaluation revealed that GCH1 was more highly expressed in cervical cancer tissue than in paracarcinoma tissue." (PMID 41583517, 2026). "This famous cancer-promoting signaling pathway in cervical cancer 31-33 was enriched in the GSVA analysis of GCH1." (PMID 41583517, 2026). "Our research revealed an interesting phenomenon: the expression of GCH1 in cervical cancer is greater than that in normal tissues, but the lower the expression in cervical cancer is, the better the prognosis." (PMID 41583517, 2026). "The genes SQLE, APOC1, H1.2, GCH1, and EEF1A1 were determined to be associated with cervical cancer." (PMID 41583517, 2026). "This could explain the elevated expression of GCH1, an oncogene, in cervical cancer tissues compared with normal tissues." (PMID 41583517, 2026). "This could explain the better prognosis for patients with high expression of GCH1 in cervical cancer." (PMID 41583517, 2026). "Interestingly, the stronger the expression of GCH1 in cancer tissue was, the better the prognosis of these patients with cervical cancer." (PMID 41583517, 2026). "GCH1 expression was much higher in cervical cancer tissue than in paracarcinoma tissue (P < 0.05)." (PMID 41583517, 2026). "GCH1 and H1.2 could act as useful prognostic markers in cervical cancer, and in addition to their connection with the tumor microenvironment, the possible transcriptional regulatory network, hallmark pathways and chemotherapy sensitivity were also clarified." (PMID 41583517, 2026). "To study whether GCH1 in cervical cancer cells affects macrophage polarization, we collected conditioned medium (CM) from GCH1-knockdown SiHa cell cultures and cultured M0 cells with the CM." (PMID 41583517, 2026). "Moreover, we identified the complexity of the function of GCH1 in cervical cancer." (PMID 41583517, 2026). "The intersection of LASSO and SVM-RFE analyses revealed eight hub genes in cervical cancer, which were RBBP4, SRM, GCH1, USP14, TRAIP, CBX4, VEZF1, and TOM1." (PMID 36999051, 2023). "Through the subsequent bioinformatics analysis, we discovered two effective ferroptosis-related molecules that have not yet been reported in cervical cancer: GCH1 and H1.2." (PMID 41583517, 2026). "GCH1 expression levels were correlated with the cervical cancer FIGO clinical stage (P < 0.05) but not with age, human papilloma virus (HPV) infection, lymph node metastasis, histological grade, or cancer recurrence." (PMID 41583517, 2026).
cervical cancer (continued). "In this study, the chemotherapy sensitivity of each cervical cancer sample was evaluated using the pRRophetic package in R based on drug sensitivity data from the GDSC, and patient sensitivities to common treatments and connections with GCH1 and H1.2 expression were investigated further." (PMID 41583517, 2026).
Cognitive impairment (2 papers, 2022 to 2025). Abnormal cognition is characterized by deficits in thinking, reasoning, or remembering. "(2022) showed that Hcy‐thiolactone induces nitrosative stress and cognitive impairment through S‐nitrosylation of GTP cyclohydrolase 1 (GCH1), an enzyme essential for tetrahydrobiopterin (BH4) biosynthesis." (PMID 41427720, 2025). "The iNOS-mediated nitrosative stress induced by HTL drives GCH1 S-nitrosylation to induce cerebral vascular stiffness and cognitive impairments." (PMID 36399957, 2022). "In light of these observations, we speculate that HHcy may induce cerebrovascular hypoperfusion and cognitive impairments through GCH1 S-nitrosylation." (PMID 36399957, 2022).
heart failure (2 papers, 2023). Inability of the heart to pump blood at an adequate rate to meet tissue metabolic requirements. "Targeting endothelial cell Gch1 and BH4 biosynthesis may provide a novel therapeutic target for the prevention and treatment of cardiac dysfunction, ischemia injury, and heart failure." (PMID 36735402, 2023). "Thus, targeting endothelial cell Gch1 and BH4 biosynthesis may provide a novel therapeutic target for the prevention and treatment of cardiac dysfunction, ischemia injury, and heart failure." (PMID 36735402, 2023). "Importantly, overexpression of GCH1 significantly rescued BHPF-mediated downregulation of BH2, and repressed BHPF-induced upregulation of ferroptosis and heart failure biomarkers, which was accompanied by relieving of BHPF-induced reduction in heart rate and cardiac viability." (PMID 38152479, 2023).
injury (2 papers, 2009 to 2024). Damage inflicted on the body as the direct or indirect result of an external force, with or without disruption of structural continuity. "Based on these findings, we propose that: i) up-regulation of GCH1 following nerve injury is associated with inflammatory activation of microglia and development of pain; and ii) GCH1 down-regulation alters microglial activation patterns, and subsequently leads to relief of pain symptoms." (PMID 19922668, 2009). "Taken together, these results indicate that the GCH1/BH4 axis is a therapeutic target for the treatment of radiation-induced acute lung injury." (PMID 38689083, 2024).
ischaemic stroke (2 papers, 2016 to 2025). "Several genes, including PITX2,ZFHX3, HDAC9, FOXF2,GUCY1A3, and GCH1, havebeen identified to increase the risk of developing ischaemic stroke." (PMID 40351662, 2025). "The GCH1 rs841 variant is reported to be associated with mildly increased blood pressure and heart rate and serves as an independent predictor of deleterious long-term outcomes in ischemic stroke." (PMID 26215833, 2016).
major depressive episode (2 papers, 2022). "A cross-sectional cohort study of those with DRD with and without GCH1 mutations also found the GCH1 mutation-positive cohort to report lower rates of self-satisfaction and higher levels of major depressive episodes prior to prescription of L-Dopa." (PMID 36201146, 2022).
myocardial ischemia (2 papers, 2012 to 2017). A disorder of cardiac function caused by insufficient blood flow to the muscle tissue of the heart. "Previously we have found that GCH1 confers the increased resistance to myocardial ischemia in Brown Norway rats compared to Dahl S rats." (PMID 22479495, 2012).
ovarian carcinoma (2 papers, 2023 to 2024). A malignant neoplasm originating from the surface ovarian epithelium. "The JAK-STAT signaling pathway, especially transcription factor STAT1, was verified to be positively correlated with GCH1-high expression, highlighting the underlying role of STAT1 in the regulation of GCH1 in breast and ovarian cancers." (PMID 36793373, 2023). "On the basis of the benefit achieved by niraparib and the inhibition of GCH1 in vitro, we sought to explore the efficacy using the ovarian cancer PDX model in vivo." (PMID 36793373, 2023). "Given the limited research on the expression and function of GCH1 in breast and ovarian cancers, we initially explored GCH1 expression and its correlation with clinicopathological characteristics." (PMID 36793373, 2023). "We further performed histochemical staining of clinical specimens derived from PDX models of breast and ovarian cancer and similarly verified that GCH1 expression was substantially higher in the niraparib-treated group compared with the control group." (PMID 36793373, 2023). "The expression of GCH1 was aberrantly enriched in breast and ovarian cancers and increased after niraparib treatment via JAK-STAT signaling." (PMID 36793373, 2023). "The results demonstrated that GCH1 expression was much higher in breast and ovarian cancers." (PMID 36793373, 2023). "We also elucidated the potential relationship between GCH1 and the homologous recombination repair pathway and proposed a combination regimen of GCH1 suppression with PARP inhibitors in breast and ovarian cancers." (PMID 36793373, 2023). "A prominent correlation of GCH1 expression with Federation International of Gynecology and Obstetrics (FIGO) stage was observed in ovarian cancer as well." (PMID 36793373, 2023). "As for ovarian cancer, the relationship between GCH1 and clinicopathology was not remarkable." (PMID 36793373, 2023).
pulmonary hypertension (2 papers, 2017). Increased pressure within the pulmonary circulation due to lung or heart disorder. "Inhibition of GCH1 activity is related to several cardiovascular diseases, with GCH1 found to prevent hypoxia-induced pulmonary hypertension." (PMID 28585439, 2017). "The overexpression of GCH1 in mice could prevent hypoxia-induced pulmonary hypertension due to the augmentation of BH4." (PMID 28585439, 2017).
rheumatoid arthritis (2 papers, 2021 to 2026). A chronic, systemic autoimmune disorder characterized by inflammation in the synovial membranes and articular surfaces. "The first signal, led by rs140884539-C (P-value = 7.05×10-08, beta = 0.59), was in strong linkage disequilibrium with variants associated with predisposition to rheumatoid arthritis, decrease in dopamine, increased levels of GCH1 transcript, dopamine metabolites, and galectin-3." (PMID 41667488, 2026).
Sepsis (2 papers, 2023). Sepsis is defined as life-threatening organ dysfunction caused by a dysregulated host response to infection. "Subsequently, we further screened two biomarkers, including Gch1 and Tnfaip3, which were associated with cellular responses to bacterial-derived molecules and lipopolysaccharides and were probably the hub molecules in the pathogenesis of sepsis-associated ALI." (PMID 38071255, 2023). "The boxplot revealed 26 differentially expressed genes between the sepsis-induced ALI and control samples: Ncf2, Slc2a6, Cd44, Txnip, Slc2a1, Ubc, Hspb1, Zfp36, Arntl, Ddit4, Tnfaip3, Txnrd1, Mt1, Hmox1, Gch1, Gclc, Stat3, Egfr, Hif1a, Bach1, Socs1, Dusp1, Cdkn1a, Fth1, Steap3, and Alox12." (PMID 37081490, 2023).
Alzheimer disease (1 paper, 2019). A progressive, neurodegenerative disease characterized by loss of function and death of nerve cells in several areas of the brain leading to loss of cognitive function such as memory and language. "These authors identified two common variants, GCH1 (rs72713460) and KCNJ15 (rs928771), showing nominal associations with Alzheimer's disease in Chinese patients." (PMID 31032141, 2019).
Arthritis (1 paper, 2022). Inflammation of a joint. "GCH1 (GTP cyclohydrolase 1) is a gene that encodes for an enzyme involved in tetrahydrobiopterin (BH4) synthesis and is associated with abnormal joint morphology and arthritis." (PMID 36680176, 2022).
attention deficit-hyperactivity disorder (1 paper, 2013). A disorder characterized by a marked pattern of inattention and/or hyperactivity-impulsivity that is inconsistent with developmental level and clearly interferes with functioning in at least two settings (e.g. at home and at school). "Deficient DA-signalling also plays a role in attention deficit hyperactivity disorder (ADHD) and GTP cyclohydrolase 1 deficiency (see GTPCH section) which leads to another movement disorder named Segawa disease." (PMID 23683503, 2013).
Borderline intellectual disability (1 paper, 2024). Borderline intellectual disability is defined as an intelligence quotient (IQ) in the range of 70-85. "Although borderline intellectual disability has been rarely reported in AD GCH1‐deficiency, cognitive function is typically preserved." (PMID 39082248, 2024).
Bradycardia (1 paper, 2024). A slower than normal heart rate (in adults, slower than 60 beats per minute). "In addition, although studies have shown that GCH1 deficiency in mice leads to bradycardia in the second trimester of pregnancy and embryonic death, the mechanism of GCH1 in protecting tissues and organs from ferroptosis remains to be elucidated." (PMID 39769097, 2024).
brain tumor (1 paper, 2022). "Moreover, GCH1 was found to be overexpressed in GBM, promoted growth, maintained the brain tumor-initiating cells and suppressed the reactive oxygen species in GBM." (PMID 36266731, 2022).
Chorea (1 paper, 2022). Chorea (Greek for 'dance') refers to widespread arrhythmic involuntary movements of a forcible, jerky and restless fashion. "In contrast, a mildly impaired but independent gait pattern was commonly observed in patients with drug‐responsive neurotransmitters defects (GCH1, DHPR, SPR, TH, and PTPS), nonprogressive chorea (NKX2." (PMID 36054588, 2022).
chronic obstructive lung disease (1 paper, 2022). "To examine whether HHcy induces GCH1 S-nitrosylation through iNOS-driven nitrosative stress, we used N-acetyl-cysteine (NAC) to block protein S-nitrosylation in vivo, which is a clinical drug used for chronic obstructive lung disease, and L-N6-1-Iminoethyl-lysine (L-NIL) to selectively inhibit iNOS." (PMID 36399957, 2022).
cleft lip (1 paper, 2016). Congenital defect in the upper lip where the maxillary prominence fails to merge with the merged medial nasal prominences. "The purpose of the study was to analyse polymorphic variants of the GCH1 gene as risk factors for non-syndromic cleft lip with or without cleft palate (NSCL/P)." (PMID 26215833, 2016).
dementia (1 paper, 2014). Loss of intellectual abilities interfering with an individual's social and occupational functions. "Although her sons showed DRD manifestation with a GCH-1 mutation and she also had a GCH-1 mutation, the diagnosis of DRD is doubtful in terms of the delayed onset, motor complications, dementia, and abnormalities on the brain scan." (PMID 24844652, 2014).
diabetic cardiomyopathy (1 paper, 2016). Diabetic cardiomyopathy is a disorder of the heart muscle in people with diabetes. "Diabetic cardiomyopathy was induced in C57BL/6 wild-type mice and transgenic mice with cardiomyocyte-specific overexpression of GCH1 with streptozotocin, and control animals were given citrate buffer." (PMID 27295516, 2016). "Here we report that reduction of cardiac GTP cyclohydrolase 1 (GCH1) degradation by genetic and pharmacological approaches protects the heart against diabetic cardiomyopathy." (PMID 27295516, 2016).
Ebola hemorrhagic fever (1 paper, 2011). A viral hemorrhagic fever that is caused by the Ebola virus, which is transmitted by contact with infected animals or humans; it is characterized by high fever, unexplained bleeding, and a high mortality rate. "However, COX-2, GCH1, GM-CSF, MIP-3α, t-Pa, GADD45A, and IDO (6 h) are genes identified to play a role in Ebola hemorrhagic fever for the first time." (PMID 22028943, 2011).
endometriosis (1 paper, 2023). The growth of functional endometrial tissue in anatomic sites outside the uterine body. "GCH1, RPL8, PKLR, and MAOA were the key targets of paeonol in the treatment of endometriosis." (PMID 36677710, 2023).
fibromyalgia (1 paper, 2018). A chronic disorder of unknown etiology characterized by pain, stiffness, and tenderness in the muscles of neck, shoulders, back, hips, arms, and legs. "Currently, no study in Caucasian population is available; therefore, future research testing associations of GCH1 gene SNPs, particularly the rs841, with fibromyalgia susceptibility in Caucasians is welcome." (PMID 29486785, 2018). "In conclusion, we identified associations of the rs841 (GCH1 gene) and rs2097903 (COMT gene) SNPs with higher risk of fibromyalgia." (PMID 29486785, 2018). "We identified, for the first time, that the rs841 (GCH1 gene) and rs2097903 (COMT gene) SNPs were associated with having fibromyalgia." (PMID 29486785, 2018). "Guanosine triphosphate cyclohydrolase 1 (GCH1) and opioid receptor μ1 (OPRM1) are candidate neurotransmitter-related genes that may confer fibromyalgia susceptibility." (PMID 29486785, 2018). "However, whether GCH1 and OPRM1 genes are associated with fibromyalgia susceptibility in the Caucasian population is unknown." (PMID 29486785, 2018).
infarction (1 paper, 2017). A localised pathological necrosis of tissue resulting from obstruction of the blood supply usually by a thrombus, an embolus, or vascular torsion. "In the present study, we examined the regulation and role of GCH1 in left ventricular remodeling after MI in mice and explored the molecular mechanisms underlying regulation of post-infarction cardiac remodeling by GCH1." (PMID 28596578, 2017). "It is possible that above BH4–mediated signaling pathways are involved in the favorable effects of GCH1 overexpression on post-infarction remodeled myocardium." (PMID 28596578, 2017). "Intriguingly, transgenic overexpression of GCH1 in cardiomyocytes reduces the thickness of interventricular septum and interstitial fibrosis and increases anterior wall thickness and cardiac contractility after infarction." (PMID 28596578, 2017). "To study whether increases in cardiac GCH1 can attenuate cardiac remodeling after MI, we made infarction in Tg and C57BL/6 WT mice by ligating the left coronary artery." (PMID 28596578, 2017). "In the current study, GCH1 overexpression elevated cardiac BH4 concentrations in both normal and post-infarction myocardium." (PMID 28596578, 2017). "It is likely that decreased GCH1 in post-infarction remodeled myocardium results from increased degradation of GCH1 by the 26 S proteasome, rather than decreased biosynthesis of GCH1." (PMID 28596578, 2017).
ischemia (1 paper, 2023). A hypoperfusion of the BLOOD through an organ or tissue caused by a PATHOLOGIC CONSTRICTION or obstruction of its BLOOD VESSELS, or an absence of BLOOD CIRCULATION. "Targeting endothelial cell Gch1 and BH4 biosynthesis may provide a novel therapeutic target for the prevention and treatment of cardiac dysfunction and ischemia-reperfusion injury." (PMID 36735402, 2023).
ischemia reperfusion injury (1 paper, 2023). Adverse functional, metabolic, or structural changes in ischemic tissues resulting from the restoration of blood flow to the tissue (reperfusion), including swelling; hemorrhage; necrosis; and damage from free radicals. "Collectively, these data demonstrate a critical role for endothelial cell Gch1/BH4 biosynthesis on coronary vascular function, cardiac function, and myocardial injury following ischemia-reperfusion injury." (PMID 36735402, 2023).
itch (1 paper, 2019). "We employed acute and inflammatory nociceptive models as well as Compound 48/80 (Cp48/80) and hydroxychloroquine‐evoked itch models to assess the functions of GCH1/BH4 in and from myeloid immune cells in the context of nociception and itch." (PMID 30450838, 2019). "GCH1 knockout reduced, and overexpression increased the scratching response in Cp 48/80‐evoked and hydroxychloroquine‐evoked pruritus, which are models for “histamine‐evoked” and “histamine‐independent” itch." (PMID 30450838, 2019).